BGN (biglycan)
Diseases named in the same sentence as BGN in open-access papers (continued):
Sharing a sentence is not in itself a finding about the gene and the disease.
tumor (continued). "In addition, tumor-associated ECs produce non-conventional growth factors such as biglycan, lysyl oxidase (LOX) and pentraxin, sustaining angiogenesis processes." (PMID 38426109, 2024). "Furthermore, Gene Expression Profiling Interactive Analysis (GEPIA) and our research underscored elevated BGN expression is tumor tissues compared to normal ones, with the low expression group exhibiting more favorable outcomes in terms of disease-free survival (DFS) and OS." (PMID 38740818, 2024). "Thus, GC patients with high BGN expression may have poorer histological types, lower tumor differentiation, more advanced tumor development, and may show greater association with HP infection." (PMID 35154268, 2022). "Furthermore, highly expression of BGN and THBS2 in tumours was linked to a worse survival rate." (PMID 36377223, 2022). "Also, biglycan depletion in stroma suppressed tumor fibrosis, consistent with a previous report." (PMID 33966638, 2021). "However, a paucity of studies have systematically assessed the function of BGN in tumor immunity." (PMID 35096572, 2021). "Biglycan has been demonstrated to trigger the synthesis of the macrophage chemoattractants chemokine (C-C motif) ligand CCL2 and CCL5; thus, it may be possible that biglycan deficiency modulates tumor vasculature through recruitment of macrophages." (PMID 33966638, 2021). "Clinically, high levels of BGN were independent of the Lauren classification and the TCGA molecular subtypes, but it was associated with the more aggressive tumor stages." (PMID 33809543, 2021). "However, the detailed mechanisms by which biglycan mediates tumor desmoplasia and hypoxia remain unclear." (PMID 33966638, 2021). "According to our current knowledge, biglycan-mediated inflammatory milieu may promote tumor growth." (PMID 31739592, 2019). "Recent studies have indicated significantly higher expression of BGN in tumor tissues compared with adjacent normal tissues, in several cancers, including endometrial cancer, pancreatic cancer, colon tumor and tumor blood vessels and esophageal squamous cell carcinoma." (PMID 24681892, 2014). "The detection of both, association of BGN with malignant properties of tumor cells and poor prognosis and the contrary in other studies including the present investigation, may be due to specific effects of BGN in the different tumor entities and/or tumor stage-dependent effects of BGN." (PMID 24223213, 2013). "However, despite this positive association with tumor staging multivariate analysis revealed that BGN mRNA expression level (p=0.155) was not an independent prognostic factor." (PMID 24223213, 2013). "However, there are few reports on biglycan expression and function in the tumour microenvironment." (PMID 22374465, 2012). "Because TLR2 and TLR4 are expressed on the endothelium and implicated in angiogenesis independent of VEGF, biglycan might stimulate tumour angiogenesis through TLR2 and TLR4 activation." (PMID 22374465, 2012). "In this study, we aimed to systematically investigate the role of BGN in PTC, focusing on its tumor-intrinsic functions and its immunomodulatory effects, particularly in driving macrophage M2 polarization and immune evasion." (PMID 41328346, 2026). "Immunohistochemical staining of tumor tissues demonstrated a positive correlation between p-AKT expression and BGN levels, with a similar trend observed in Ki67-positive cell rates." (PMID 41328346, 2026). "Our results demonstrated that BGN expression in tumor cells and fibroblasts was positively correlated with later T stage and TNM stage, whereas BGN expression in endothelial cells and smooth muscle cells was inversely correlated with aggressiveness." (PMID 41328346, 2026). "We found that NR2F2 directly binds to both the BGN enhancer and promoter regions, activating BGN transcription, thereby driving PTC tumor progression and the formation of an immunosuppressive microenvironment." (PMID 41328346, 2026).
tumor (continued). "BGN also acts in a paracrine manner via TLR4 receptors on macrophages to induce M2 macrophage polarization, contributing to an immunosuppressive tumor microenvironment." (PMID 41328346, 2026). "Treatment with the NR2F2 inhibitor CIA1 blocks NR2F2 activation of BGN, reducing BGN expression and AKT pathway activity, inhibiting malignant behavior of tumor cells, and reversing macrophage polarization, thereby restoring antitumor immunity." (PMID 41328346, 2026). "Meanwhile, Domain 4 expressed tumor-suppressive genes like DCN, LUM, BGN, and COL1A2, suggesting a protective microenvironment." (PMID 40838787, 2025). "A further investigation of myoferlin in the context of tumor-restraining ECM components, such as collagen XV and biglycan is necessary to validate a specific tumor-promoting ECM function of myoferlin." (PMID 41062852, 2025). "LUM, COL18A1, BGN, PRELP, and ASPN showed increased expression in tumor tissue compared to the paired NAT tissue, inconsistent with the declined trend in other histologic subtypes." (PMID 39305996, 2024). "In light of the Thakur study highlighting stromal BGN as a TGF-β inhibitor and tumor suppressor in a murine model of human PDAC, we were especially interested in revealing if all three proteins do affect TGF-β signaling." (PMID 38255305, 2024). "In the present study, tumor cells were observed to be reduced in BM and highly expressed MUC1, SCGB2A2, FN1, BGN, and PEG10." (PMID 37470685, 2023). "BGN and FAP were also positively correlated with advanced TNM, poor tumor differentiation, LNM, and postoperative PM according to the 8th edition of the AJCC Cancer Staging Manual." (PMID 36632455, 2023). "The protein expression levels of AEBP1, BGN, and TAGLN in tumor tissues were higher than those in normal tissues." (PMID 36523769, 2022). "According to the Human Protein Atlas database, we found that the protein expression levels of AEBP1, BGN, and TAGLN in tumor tissues were higher than those in normal tissues." (PMID 36523769, 2022). "Further studies verify that ASPN expression is low in non-tumor tissues, including breast tissue, on the contrary to DCN and BGN, which present high expression levels in normal tissues." (PMID 36358747, 2022). "To elucidate the role of BGN in BCSCs, we generated CRISPR mediated knockout of BGN in FF99 cells (PyMT tumor derived cells,) using mouse specific sgRNA." (PMID 35053617, 2022). "The results show an abundance of ECM proteins, such as collagens, and remodeling enzymes (BGN, FAP) in tumor tissue, compared to the normal tissue." (PMID 35328635, 2022). "The role of BGN proteoglycan has been evaluated in lung tumor tissue microenvironment (TME) as a metastasis factor, recommending inhibition of stromal BGN as a tumor vascular normalization element." (PMID 36139528, 2022). "TN stage correlation analysis demonstrated BGN, GRK5 and SREBF1 were closely correlated tumor progression." (PMID 34116604, 2021). "As an SLRPs family, biglycan is significantly higher in CRC tissues than that of corresponding normal tissues, which is related to poor tumor differentiation, lymph node metastasis, and distant metastasis." (PMID 34502094, 2021). "We assessed the capacity of GC cells in tumor formation and its angiogenic potential using the chick embryo choriallantoic membrane (CAM) xenograft model in order to investigate the role of biglycan expression in vivo." (PMID 33809543, 2021). "Our previous report revealed that BGN enhances tumor cell migration through the activation of Nuclear factor kappa B (NF‐κB) and ERK signaling via Toll‐like receptors and induced tumor cell intravasation and metastasis." (PMID 33709550, 2021). "Furthermore, as biglycan activates the NF-κB signaling pathway, which is one transcriptional activator of PD-L1, we speculate that biglycan may induce PD-L1 expression in tumor cells." (PMID 33966638, 2021).
tumor (continued). "Six tumor antigens (THBS2, FSTL3, TNNT1, BGN, CTHRC1, and NOX4) were identified as potential therapeutic candidates for the anti-CRC mRNA vaccine that can be processed and presented by APCs to activate a robust immune response." (PMID 35127707, 2021). "To verify the reliability of these bioinformatics evaluations, we carried out RT-qPCR to assess expression of hub genes (BGN, SPP1, LINC01614, and LINC01415) in clinical tumor samples." (PMID 33362844, 2020). "Tumor endothelial cells also hypomethylate the BGN promoter, epigenetically promoting biglycan expression and supporting tumor vascularization in metastatic cancers." (PMID 33020183, 2020). "BGN and SPP1 are essential components of the extracellular matrix, which has a critical role during the migration and progression of tumor cells." (PMID 33362844, 2020). "High expression of SPP1, BGN, LINC01614, and LINC01415 in tumor samples was validated further by RT-qPCR." (PMID 33362844, 2020). "Expression of BGN, SPP1, LINC01415, and LINC01614 was much higher in tumor samples than in normal esophageal tissues." (PMID 33362844, 2020). "In vitro examination showed that biglycan is involved in TEC migration and tube formation, and biglycan secreted from TECs stimulates tumor cells to metastasize to lungs." (PMID 31533313, 2019). "Among the top differentially expressed genes between tumor and DTC samples, we found genes involved in metastasis initiation and angiogenesis, for example, MGP, BGN, POSTN and ANGPT2, to be upregulated in tumors." (PMID 28921546, 2018). "We found that collagen, biglycan, fibulin 2, and FSTL1 can induce tumor cell invasion under the bead, though only collagen seemed to allow cells to migrate through the bead." (PMID 29615735, 2018). "The mechanism of the effects of BGN on tumor cell migration is likely to be mediated by the Rac1-mediated TGF-β signaling pathway, thus suggesting a role of BGN in the development of EMT29." (PMID 28687755, 2017). "In addition, biglycan may also act as a chemoattractant for tumour cells, in addition to TECs23." (PMID 27295191, 2016). "Thus, high biglycan expression may positively correlate with tumour progression." (PMID 27295191, 2016). "Biglycan promoted tumour cell migration, and biglycan knockdown in HM-TECs inhibited tumour migration toward HM-TECs and decreased numbers of CTC and tumour metastasis." (PMID 27295191, 2016). "In terms of N stage, BGN secreted by tumor cells was highly expressed in the lymph node metastasis group, but BGN secreted by fibroblasts was not related to N stage." (PMID 41328346, 2026). "Immunohistochemical analysis of tumor tissues demonstrated that CIA1 treatment downregulated BGN, Ki67, and p-AKT expression, while NR2F2 and total AKT levels remained unchanged, suggesting that CIA1 primarily acts through inhibition of the NR2F2-BGN axis." (PMID 41328346, 2026). "Furthermore, we explored the enhancer-dependent transcriptional regulation of BGN by NR2F2, elucidating how the NR2F2-BGN axis contributes to tumor progression and immunosuppressive microenvironment formation." (PMID 41328346, 2026). "Within the TME, spatial transcriptomics and scRNA-seq revealed that CAFs, rather than tumor cells, exhibited the highest BGN expression." (PMID 41833003, 2026). "Moreover, BGN's activation of innate immune receptors such as TLR2 and TLR4 further underscores its potential as a universal modulator of tumor immunity." (PMID 41328346, 2026). "Decorin and lumican can suppress growth factor signaling (e.g., TGF-β and EGFR), while biglycan may promote inflammatory signaling through TLR2/4, underscoring their dual tumor-suppressive and tumor-promoting roles." (PMID 41228294, 2025). "Additionally, we found thatPDK1 silencing inhibited the subcutaneous tumor growth and peritoneal metastasis of EOC in mice, whereas increased BGN partially reversed these results." (PMID 39578715, 2024).
tumor (continued). "Tissue multiplex immunofluorescence revealed widespread presence of BGN + Fib in tumor tissues, while it was almost absent in adjacent normal tissues." (PMID 38654221, 2024). "These include CTHRC1, INHBA, BGN, and PDPN, all of which are known to promote tumor progression." (PMID 38036590, 2023). "Biglycan concentration was highest in tumor-bearing WT mice compared to non-tumor WT mice and tumor-bearing Bgn KO mice." (PMID 33966638, 2021). "While biglycan is mostly known as a structural element of the ECM, more recent studies have identified critical roles for increased biglycan expression in tumor initiation and progression by playing a role as a signaling molecule in the regulation of inflammation, angiogenesis and autophagy." (PMID 35008869, 2021). "We therefore hypothesized that ANGPT2 might be regulated by biglycan/TNF-α signaling, leading to the destabilization of tumor blood vessels." (PMID 33966638, 2021). "We found that Hif1a and Slc2a1 expression elevation in E0771 cells by stimulation with recombinant biglycan, which indicated that biglycan might mediate HIF1-α and Glut1 expression in tumor cells." (PMID 33966638, 2021). "In addition, biglycan can directly increase VEGFA expression in colon cancer cells, thereby promoting tumor angiogenesis and cancer growth." (PMID 34502094, 2021). "As activated cancer-associated fibroblasts (CAFs) in tumor stroma is involved in tumor fibrosis and activated CAFs can be identified by their expression of α-SMA, α-SMA+ fibroblast (excluded pericytes) assessment by staining was analyzed in biglycan KO mice." (PMID 33966638, 2021). "As hypoxic response is mainly ascribed to hypoxia-inducible factor-1 (HIF-1) α which is involved in the induction of Glut1 expression, we checked whether biglycan affects HIF1-α and Glut1 expression in tumor cells." (PMID 33966638, 2021). "The expression levels of BGN protein were significantly elevated in tumor tissues, as compared with in the adjacent noncancerous tissues (MOD = 0.140 ± 0.023 vs 0.133 ± 0.026, p = 0.003)." (PMID 35096572, 2021). "We observed that both tumors formed by WT or biglycan KO cells grow in multiple foci and not as a single tumor mass at the injection site (arrows/circles)." (PMID 33809543, 2021). "Due to the ability of biglycan to affect ROS production via TLR2 and TLR4 in a NOX1- and NOX4-dependent manner, it is very likely that biglycan potentially influences tumor angiogenesis via ROS level regulation." (PMID 34917515, 2021). "Importantly, compared to normal tissues, extremely high correlations were observed among AEBP1, BGN, POST, and FAP in COAD, suggesting that the STMERN specifically formed in tumor tissues." (PMID 34239578, 2021). "Induced overexpression of biglycan in HER‐2/neu cells increases MHC class I expression and decreases miR‐21‐3p, highlighting the vital role of biglycan in the MHC class I‐driven immune escape in tumor cells." (PMID 34917515, 2021). "In this regard, DCN is considered as a potent natural inhibitor of tumor cell proliferation and invasion, whereas the other proteoglycans, namely, versican and biglycan, are not." (PMID 34884232, 2021). "We observed that the biglycan protein is mostly absent in normal gastric glands and highly expressed in metaplasia and in tumor samples." (PMID 33809543, 2021). "Since biglycan is mostly an ECM-associated protein, it is not unexpected to see intense staining in the ECM compartment around the tumor, where cancer-associated fibroblasts and infiltrating macrophages and immune cells are present." (PMID 35008869, 2021). "The main mechanism of biglycan signaling employs TLR2 and TLR4 receptors and results in pro-tumorigenic effects, including the production of cytokines and growth factors that ultimately promote tumor angiogenesis." (PMID 34917515, 2021).
tumor (continued). "Together, these data suggested that alleviating tumor hypoxia by biglycan knockout might be due to enhancement of vascular normalization and mediation of HIF1-α and Glut1 expression in tumor cells." (PMID 33966638, 2021). "As E0771 cells had low expression of biglycan in vitro, these results suggested that stroma biglycan is involved in lung metastasis but not in tumor growth, consistent with our previous report showing induction of metastasis by biglycan-secreting TECs." (PMID 33966638, 2021). "We have found that biglycan increased HIF1-α and Glut1 expression in tumor cells." (PMID 33966638, 2021). "Biglycan is a small leucine-rich proteoglycan (SLRP) and is mainly known for its role in the ECM and infiltrating immune cells in the stroma, which shape the tumor microenvironment." (PMID 35008869, 2021). "This might be explained by possibly different cellular effects of decorin and biglycan via TLR signaling found for example in tumor cells, where opposite effects of these proteoglycans on tumor growth via TLR have been shown." (PMID 32731559, 2020). "Biglycan is a small leucine-rich proteoglycan that, unlike decorin and endorepellin, promotes neovascularization in the tumor microenvironment." (PMID 33020183, 2020). "The results demonstrated that for all kinds of tumor spheroids (primary, TMD, and BMD cells), collagen, biglycan, and osteonectin decreased spheroid size similarly to osteocyte-conditioned media, though the degree of decrease varied among the three kinds of tumor cells." (PMID 29615735, 2018). "Next we examined the immunoreactivity for two stromal PGs, namely DCN and BGN, in this MBC tumour." (PMID 28653173, 2017). "Our data revealed that TECs and other stromal cells, but not tumour cells, expressed biglycan in HM-tumours." (PMID 27295191, 2016). "Similarly, pretreatment of tumour cells with U0126, a specific inhibitor of mitogen-activated protein kinase (MEK) 1 and 2, decreased the number of tumour cells migrating toward biglycan." (PMID 27295191, 2016). "Biglycan upregulation in HM-TECs was maintained for several months, although all ECs had been cultured under the same conditions without the addition of any tumour-derived factors." (PMID 27295191, 2016). "Strong biglycan expression was detected in tumour blood endothelial cells of a metastatic case (case number 16) but was barely detected in the tumour tissues of a nonmetastatic case (case number 11)." (PMID 27295191, 2016). "In contrast asporin and biglycan was not expressed in normal tissues but was found to be expressed in the tumor stroma." (PMID 24634138, 2014). "Immunohistochemistry staining showed BGN expression was higher in tumor tissues than that in non-tumors tissues, and showed that BGN is mainly located in cytoplasm of epithelial cells." (PMID 24681892, 2014). "BGN staining in human tumor samples revealed only faint signals in stromal tissue of non-invasive Ta and T1 tumors." (PMID 24223213, 2013). "As we screened the samples for the immunoreactivity for another, very similar SLRP to decorin, namely biglycan, we found that the tumour areas negative for decorin were positive for biglycan immunoreactivity." (PMID 24146840, 2013). "In this context, it is of interest that soluble BGN serves as a ligand for TLR4 and TLR2, which might explain some of the anti-tumor effects of BGN." (PMID 24223213, 2013). "We also found that biglycan mRNA was hardly expressed in human tumour stromal cells, which were negative for CD31 in a human fibroblast cell line, BJ-6, (data not shown)." (PMID 22374465, 2012). "In in vivo tumour tissues, biglycan was stained in tumour blood vessels but was not or weakly stained in tumour cells and CD31-negative stromal cells including fibroblasts." (PMID 22374465, 2012).